MMP1 (matrix metallopeptidase 1)
Diseases named in the same sentence as MMP1 in open-access papers (continued):
Sharing a sentence is not in itself a finding about the gene and the disease.
tumor (continued). "MMP-3 also has a role in activation of proMMP-1 in tumor tissue into the active form of MMP-1." (PMID 17919326, 2007). "In addition, Runx2 has the potential to regulate the transcription of extracellular matrix modulators such as SPARC and MMP1, thereby influencing the tumour microenvironment." (PMID 17876328, 2007). "Our TMA results also highlight the potentially important contribution of MMP-1 production by stromal cells and indicate that tumour/stromal interactions may play a critical role in modulating gene expression to effect prognosis in patients with CRC." (PMID 17311017, 2007). "Hence, we speculated that Binpu-3RE may interfere with the EMT process by inhibiting the expression of β-integrin and MMP1, thereby regulating tumor metastasis." (PMID 40151788, 2025). "Moreover, Matrix Metalloproteinase 1 (MMP1) has been demonstrated to have a significant correlation with cellular aging across various cell types and exhibits elevated expression levels in numerous tumor tissues." (PMID 39580409, 2024). "Thus, angiogenic factors may favor the detachment of OSCC cells from the primary tumor by both reducing E-cadherin levels and upregulating MMP-1." (PMID 39120324, 2024). "Finally, qRT-PCR revealed that the abundance of DOHH, P4HA3 and MMP1 were high in tumor cases, indicating the complex mechanism between the high expression of DOHH as a protective factor and the high expression of P4HA3 and MMP1 as the risk factors in the development of GC." (PMID 37957566, 2023). "Similarly, in TCGA and GEO datasets, MMP1 was also upregulated in tumor tissues and metastasis." (PMID 37484321, 2023). "MMP1, a member of the Matrix metalloproteinase family of proteases that degrade the extracellular matrix during physiological processes, including embryonic development and tissue remodeling, have been subsequently found to be upregulated in nearly every tumor type." (PMID 36701406, 2023). "Interestingly, early-stage tumor cells are able to produce high levels of EREG as well as MMP-1." (PMID 37447165, 2023). "It has been reported that MMP1 could improve tumor resistance by regulating CAFs in HNSC." (PMID 36727076, 2022). "In the present study, our results indicated that MMP1 expression was significantly increased in patients with perineural invasion and that hypoxic conditions may increase the expression of MMP-1 in human primary tumors, which might help transplanted tumor cells spread and evade in mice." (PMID 35444950, 2022). "In addition, high MMP1 expression was related to poor DFS in 6 tumor types." (PMID 36727076, 2022). "Thus, HYP and MMP-1 can be used as markers of skin aging process." (PMID 36249807, 2022). "Besides, the expression levels of RUNX2 and MMP1 in tumor sections from both groups of xenograft tumor were detected by immunohistochemical staining, which showed that they were obviously lower in tumors of the shRUNX2 group compared with those of the NC group." (PMID 36483054, 2022). "MMP-1 high expression proved to be a risk factor for tumor recurrence and independent molecular marker of prognosis in HCC and may become a novel target in the strategies for the prediction of tumor progression and prognosis of this disease." (PMID 33369474, 2020). "Since orobol showed a potent anti-skin-aging effect via the inhibition of MMP-1 expression at a concentration range of 4–8 μM, it can be claimed that the prepared NLCs formulation can provide sufficient epidermal/dermal orobol concentration to exert its anti-skin-aging effect." (PMID 32899309, 2020).
tumor (continued). "We previously reported that KLK4 induces cancer-associated fibroblast features in prostate-derived stromal cells, induces epithelial to mesenchymal transition (EMT)-like characteristics, and activates matrix metalloproteinase-1 (MMP-1), which, together, could impact tumor growth and metastasis." (PMID 33255452, 2020). "The increased expression of MMP-1 in human chondrosarcoma is an important prognostic factor and its function in the spread of tumor cells has been evaluated by silencing assays in which cancer metastasis is impaired but local tumor growth and angiogenesis are enhanced." (PMID 31921634, 2019). "The MMP1–1607 (1G>2G) polymorphism has been associated with increased transcription of MMP1 due to an insert of a guanine base that creates a core-binding site for the EST family of transcription factors, which leads to increased susceptibility for tumor occurrence and progress." (PMID 30627228, 2018). "In addition, BGN and MMP1 were both upregulated in the epithelial tumor cells." (PMID 28687755, 2017). "Since up-regulation of MMP1 might result from activating NF-κB signaling in many cell types like tumor cells and mesenchymal stem cells, we found that PMPs markedly increased the p-IκB and p-NF-κB, manifesting the positive effect of PMPs on activating NF-κB signaling in RA-FLSs." (PMID 28704431, 2017). "Furthermore, we have shown that the co-expression of gene sets that contain CXCL13 and the gene sets that contain MMP1 is affected by ER status too, in addition to tumor grade which couldn’t have been elicited in a typical univariate DCX analysis." (PMID 29297310, 2017). "While it is well documented that MMP-1 cleaves extracellular matrix molecules, such as collagen, MMP-1 has also been linked to the promotion of cell survival, suggesting that MMP-1 may contribute to multiple processes during tumor growth and progression." (PMID 26215578, 2015). "Though other MMPs (e.g., MMP-1, -2, -8, -9, -13) have been linked to degradation of laminin, vitronectin, fibronectin, enactin, collagen I-IV, MMP-10 has been identified as a stromelysin which can degrade various proteoglycan components of the ECM, thus facilitating tumor cell dissociation." (PMID 24885595, 2014). "In addition, attenuation of MMP-1 expression reduced tumor-induced angiogenesis in vivo." (PMID 24392031, 2013). "However, MMP-1 has also been shown to be required for migration and xenograft tumor formation by MDA-MB-231 cells through cleavage and activation of protein activated receptor-1 (PAR-1), such that autocrine activation of specific cellular proteins is an alternative mechanism for MMP-1 function." (PMID 25339983, 2013). "Thus, the data suggested that Ab could directly contribute to the invasive capability of scrib−+ab tumour cells by controlling the expression of migration-associated genes, including JNK targets such as Mmp1." (PMID 23874226, 2013). "Thus, Boström's study provides stronger evidence that the expression of MMP-1 in stromal fibroblasts of BC help to identify patients with atypical tumor-stromal fibroblasts in which MMP-1 may contribute to BC invasiveness and metastatic behavior." (PMID 21834986, 2011). "As highlighted by Boström and colleagues, MMP-1 expression in both stromal and tumor cells may control BC progression, suggesting that BC metastasis and outcome are driven by complex and reciprocal interactions between epithelial cancer cells and their stromal microenvironment." (PMID 21834986, 2011). "The differences in the mean tumor volume in two groups were statistically significant at 2, 4, and 5 weeks, (p<.04) (control = 349±79; MMP1 = 900±180 mm3 2 wks, control = 3568±277; MMP1 = 4690±404 mm3 4 wks, and control = 5636±615; MMP1 = 7891±716 mm3 5 wks respectively)." (PMID 21170377, 2010).
tumor (continued). "In this series, the expression of MMP-1 both in tumor and in peritumoral fibroblasts, and of MMP-11 in neoplastic cells, could explain the phenomenon of break-down of cell elements related to the blood vessel wall, such as type IV collagen, laminin and fibronectin." (PMID 18954439, 2008). "Thus, we hypothesize that the lower MMP1 levels observed in plasma could reflect a concentration of MMP1 in the tumour microenvironment." (PMID 18366705, 2008). "However, in tumor-derived fibroblasts, there was an inverse relationship with MMP-1 genotype, with lower levels of invasion generated by donors with the high-expressing 2G/2G genotype compared with the 1G/2G or 1G/1G genotypes (p = 0.08 and 0.03, respectively)." (PMID 17922906, 2007). "Among the most significantly downregulated proteins were matrix metalloproteinases (MMP‐1, MMP‐9) and uPAR, all of which are central to ECM degradation, tumor cell migration, and vascular invasion." (PMID 41474368, 2026). "Based on the multiplex immunoassay profiling, we observed that there were higher expressions of VEGF-A, MCP-1, MMP-1, TNF-α, and CD40L in the CSF samples of CPP patients in comparison to non-tumor patients." (PMID 40843692, 2025). "Mechanistically, HMMR promotes tumor metastasis by binding to mitogen-activated protein kinase kinase kinase kinase 4 (MAP4K4), which activates the p-JNK/p-c-JUN/MMP1 signaling cascade." (PMID 39990663, 2025). "In the analysis of PDAC tissues, MMP-1 was found to be significantly elevated, suggesting its involvement in PDAC progression, particularly in enabling tumor cells to invade surrounding tissues." (PMID 39869563, 2025). "Downstream analysis of genes involved in the migration of tumor cell lines revealed that MSI2 was the top regulator of migration, with a log ratio of 4.514, followed by MMP3, MMP1, and IL1β." (PMID 39990676, 2025). "Upregulated pro-inflammatory chemokines CXCL6 and CXCL5, along with ECM-degrading enzymes MMP1 and MMP13, create a feedback loop that sustains inflammation and facilitates tumor-supportive immune infiltration." (PMID 40604111, 2025). "Mechanistically, our data reveal that knockdown of KRAS inhibits matrix metalloproteinase (MMP1), MMP3, and MMP9, which are known as tumor metastasis-related proteins, via an IL-17 signal-dependent manner." (PMID 40486048, 2025). "Understanding the multifaceted roles of MMP1, particularly its dual impact on ECM remodeling and immune modulation, is crucial for uncovering mechanisms of tumor progression and immune escape." (PMID 40394037, 2025). "PAR1‐dependent tumor growth was mediated by MMP1, as treatment with an MMP‐1 inhibitor resulted in an 82% inhibition of tumor growth." (PMID 40969301, 2025). "Our RT-qPCR results confirmed the upregulation of MMP1, TFRC, and CXCL8 in the tumor group, which was consistent with the findings of our previous analyses." (PMID 40809844, 2025). "Further investigation using hematoxylin and eosin staining and immunohistochemistry staining showed that MMP1 was indeed specifically expressed in PanIN, a precursor to PDAC, suggesting its role in tumor initiation." (PMID 40092486, 2025). "Targeting MMP1 and its downstream signaling pathways, such as the ANXA1-FPR3 and CXCL16-CXCR6 axes, represented a promising therapeutic strategy to disrupt these tumor-promoting mechanisms and enhance anti-tumor immunity." (PMID 40394037, 2025). "MMP1 expression correlated with enhanced macrophage infiltration and impaired CD8+ T-cell function, contributing to an immunosuppressive tumor microenvironment." (PMID 40394037, 2025). "Among these, matrix metalloproteinase (MMP) family members—including MMP1, MMP3, MMP9, and MMP11—exhibited significant upregulation, consistent with their established roles in promoting tumor invasiveness." (PMID 40361356, 2025).
tumor (continued). "IFP has been shown to induce endothelial sprouting by upregulation of MMP1, facilitating angiogenesis in tumors, with tumor IFP increasing following the initiation of tumor angiogenesis." (PMID 39849659, 2025). "Notably, MMP1 may promote immune evasion by creating a TME that favors tumor growth and survival." (PMID 40394037, 2025). "Collectively, these findings indicate that araliadiol attenuates AP-1 activation and suppresses MMP-1 and MMP-3 expression in senescent dermal fibroblasts, thereby potentially protecting against ECM degradation and skin aging." (PMID 41471076, 2025). "RT-qPCR analysis confirmed the significant upregulation of MMP1, TFRC and CXCL8 in tumor tissues, consistent with our previous differential gene-expression studies." (PMID 40809844, 2025). "TGF-β facilitates EMT, enabling tumor cells to detach, invade, and survive in the circulation, while SASP-driven MMP1, MMP3, and other matrix metalloproteinases degrade the ECM (extracellular matrix), creating physical pathways for tumor dissemination." (PMID 41373662, 2025). "OC cell lines here show that MMC effects on both forms of the secreted protein are annihilated by hypoxia, proving that although the drug treatment and tumor microenvironment (TME; hypoxia) are activators of MMP1, their action can counteract one another." (PMID 40584967, 2025). "To explore the roles of MMP1 and TFPI in the tumor microenvironment, we analyzed their expression distributions at the single-cell level." (PMID 41425594, 2025). "The results of this study suggest that Binpu-3 root extract (Binpu-3RE) inhibits tumor cell metastasis via regulation of Notch signaling activity and the expression of EMT-related factors β-integrin and matrix metalloproteinase-1 (MMP1)." (PMID 40151788, 2025). "Studies have shown that RUNX2 is involved in tumor cell migration and invasion 23 and that RUNX2 directly targets the MMP1 promoter in TNBC cells." (PMID 40386045, 2025). "This analysis demonstrated that expression levels of MMP1 and MMP12 were increased in patients with residual tumors post-treatment, whereas RAF1 expression was higher in patients who were tumor-free post-treatment." (PMID 40362553, 2025). "MMP1 expression is elevated in RCC tissues and correlates with tumor grade, stage, and overall survival in RCC patients." (PMID 40386045, 2025). "MMP1 contributes to drug resistance through mechanisms such as ECM remodeling, promoting tumor angiogenesis, and activating other resistance-related molecules, which complicates treatment outcomes." (PMID 40287412, 2025). "The immunoreactivity of MMP-1 and MMP-3 in tumor cells was significantly higher than in normal tissues." (PMID 40564842, 2025). "Mechanistically, HMMR promotes tumor metastasis by interacting with MAP4K4, which in turn activates the p-JNK/p-c-JUN/MMP1 signaling pathway." (PMID 39990663, 2025). "When we focused on different expressed genes in a pathway related to tumor development, there were some important oncogenes correlated with JAM2, such as JUN, MMP1, CDH1, and so on." (PMID 39838844, 2025). "MMP-1, or matrix metalloproteinase-1, is capable of degrading the extracellular matrix (ECM) and plays a significant role in both inflammation and tumor progression." (PMID 39976778, 2025). "The expression levels of MMP1, TFRC, and CXCL8 were significantly upregulated in the tumor group compared to the normal group (p < 0.05)." (PMID 40809844, 2025). "In contrast to claudin-1, meta-analysis suggests that MMP-1, MMP-2, MMP-9, and VEGF are highly expressed in RB, which are highly correlated with poor cell tumor differentiation, tumor invasion, and clinically advanced stage." (PMID 38920989, 2024). "The results showed that ANXA5, MMP1, MTR, REN, SCN4A, and SMAD3 were upregulated in HC samples, while HP and ACOX1 were downregulated in tumor tissues." (PMID 38599581, 2024).
tumor (continued). "Subsequent analyses showed a complex relationship among AGBL4, MMP-1, and other inflammatory genes in regulating the GBM tumor microenvironment, affecting tumor behavior and patient survival." (PMID 39007144, 2024). "Here, we observed that CAFs grown in 3D cultures upregulated a variety of MMPs such as MMP-1, MMP2, MMP3, and MMP9, which are major players in tumor angiogenesis, tissue remodeling, repair, and maintenance." (PMID 39700125, 2024). "As expected, MMP1, MMP3, MMP12, and SPP1 displayed significantly higher expression in tumor tissues compared to normal samples." (PMID 39596132, 2024). "Our analysis using the HNSCC dataset of TCGA database revealed significantly elevated expression of MMP1, MMP3, MMP12, and SPP1 in tumor tissues compared to normal tissues." (PMID 39596132, 2024). "The results indicated that knocking down SPHK1/MMP1 reduced tumor growth rates in mice, whereas overexpression of SPHK1/MMP1 accelerated tumor growth." (PMID 39629135, 2024). "MMP1 facilitates tumor cell invasion and metastasis predominantly by ECM degradation, particularly collagen and other ECM components, thereby enabling tumor cells to breach the basement membrane and infiltrate adjacent tissues." (PMID 39600313, 2024). "The most significant findings included the transcriptional upregulation of MMP1 (125-fold), ADAM28, MMP9, and ADAM9 (5.2-fold, 4.4-fold, and 4.2-fold upregulated) in tumor tissue compared to normal skin." (PMID 38891088, 2024). "One of the studies discovered that exosomal GP73 secreted by tumor cells can enter other acceptor tumor cells with low GP73 expression, activating GSK-3β phosphorylation and inducing upregulation of MMP-1 and MMP-9, promoting tumor metastasis." (PMID 39845976, 2024). "On the other hand, from methylation analysis, we observed that the promoter region of HGs such as KRT19, MMP1, COL11A1, SDC1, FN1, and COL5A1 is significantly methylated in normal tissue than in tumor tissue." (PMID 38639039, 2024). "Collagen I fragments cleaved by MMP1, 2, and 14 activate the DDR-1 receptor enhancing tumor growth in pancreatic cancer, thereby reducing patient survival." (PMID 38659022, 2024). "The collagenases we found to be secreted in a PKD-regulated manner, MMP-1 and MMP-13, are released by tumor cells to degrade both the basement membrane and the ECM to allow cancer cell invasion and metastasis to distant organs." (PMID 38323010, 2024). "As we know, MMP1 is identified as a matrix metalloproteinase capable of degrading various components of the extracellular matrix (ECM), facilitating tumor cell invasion and metastasis." (PMID 38870261, 2024). "Conversely, knocking down SPHK1/MMP1 downregulated PD-L1+ cells and relatively increased the density of CD8+ T cells in the tumor area." (PMID 39629135, 2024). "On the day of tumor capture, IFN-γ and TNF-α ELISAs were performed on sera from HNSCC mouse models with knockout or overexpression of SPHK1/MMP1, with the results showing that SPHK1/MMP1 expression was negatively correlated with IFN-γ and TNF-α." (PMID 39629135, 2024). "In this study, we noticed that the promoter regions of five HGs, such as KRT19, MMP1, COL11A1, SDC1, FN1, and COL5A1 were highly methylated in normal compared to tumor patients." (PMID 38639039, 2024). "Next, we investigated the mRNA expression of MMP1, MMP9 and FMOD in tumor cells after they were cocultured with different CAFs in 2D." (PMID 38822309, 2024). "After euthanizing the mice and harvesting the tumors, immunofluorescence staining revealed that SPHK1/MMP1 overexpression significantly enhanced PD-L1+ cell counts and decreased the density of CD8+ T cells within the tumor region." (PMID 39629135, 2024). "MMPs, including MMP-1 and MMP-10, known for their roles in esophageal tumorigenesis, were also found to be upregulated in tumor samples." (PMID 39123475, 2024).